LMNA (lamin A/C)
Diseases named in the same sentence as LMNA in open-access papers (continued):
Sharing a sentence is not in itself a finding about the gene and the disease.
dyslipidemia (9 papers, 2011 to 2023). "LMNA missense mutations are also reported in patients with metabolic syndrome, although genetic causality was not established." (PMID 28663758, 2017). "Hyperlipidemia or dyslipidemia has also been reported in carriers of LMNA mutations." (PMID 37303410, 2023). "Indeed, beside the typical FPLD2, LMNA mutations have also been involved in a few cases of severe metabolic syndrome." (PMID 32842478, 2020). "In a separate study of 87 ‘typical’ metabolic syndrome patients, 10 patients had perturbed lamin A/C distribution and nuclear shape defects: among these, two patients had a LMNA variant (p.G411D or p.G631D), and a third patient had a ZMPSTE24 mutation and accumulated farnesylated prelamin A." (PMID 28663758, 2017). "LMNA missense mutations were identified in two studies of metabolic syndrome patients." (PMID 28663758, 2017). "Notably, several mediator CpGs reside in the proximity of well-established dyslipidemia genes: cg21922478 (ITGA1) and cg22976567 (LMNA)." (PMID 33823916, 2021).
neuroblastoma (9 papers, 2012 to 2024). Neuroblastoma (NB) is the most common solid, extracranial childhood tumor. "In agreement with these works, in previous papers we also found that LMNA expression was related to a less malignant phenotype in human neuroblastoma." (PMID 34680461, 2021). "In NTRK1-expressing cells, however, we observed a translocation of LMNA to the nucleus where it was localized within intra-nuclear aggregates in the four neuroblastoma cell lines analyzed: IMR5, SH-SY5Y, NGP and SKNAS." (PMID 34771457, 2021). "In lymphoma, leukemia, and neuroblastomas, the LMNA gene is silenced via hypermethylation of the CpG island promoter, and demethylating agents have been shown to increase lamin A/C levels in neuroblastoma cells." (PMID 33316938, 2020). "For example, CpG island promoter hypermethylation leads to lamin A/C silencing in lymphoma and neuroblastoma cells." (PMID 31015297, 2019). "In lymphoma and leukemia, and in a subset of neuroblastoma cells, hypermethylation of CpG islands at the LMNA gene promoter lead to reduced lamin-A/C expression." (PMID 29637811, 2018). "We also demonstrates that the development of TICs is due to an increased expression of MYCN gene and that in neuroblastoma exists an inverse relationship between LMNA and MYCN expression." (PMID 26439802, 2015). "We have also studied the effect of LMNA knock-down in other two neuroblastoma cell lines, IMR-32 and SMS-KCNR." (PMID 23049808, 2012). "While the data presented here indicate that NTRK1 expression and activation also interfere with LMNA-S22 phosphorylation and nuclear lamina organization, it will require further work to dissect the impact of kinase-mediated LMNA phosphorylation on replication in neuroblastoma cells." (PMID 34771457, 2021). "Overall, cells, which lack lamin A/C can have a more stem cell-like phenotype, which is shown in several tumor subtypes, such as squamous cell carcinoma, gastric carcinoma, and neuroblastoma, where lamin A/C downregulation results in poor differentiation and a more stem cell-like phenotype." (PMID 33316938, 2020). "Furthermore, lamin-A/C depletion in unmethylated neuroblastoma cells exacerbates their tumoral properties." (PMID 29637811, 2018). "Different experimental approaches pointed to a potent translocation of AGO2 into the nucleus in SHSY5Y neuroblastoma, A375 melanoma cells, HEK293 kidney cells, and U2OS bone cancer cells upon silencing of LMNA expression." (PMID 38994560, 2024). "Uncovering the differential phosphorylation of LMNA and STMN1 upon NTRK1 activation gives new clues on NTRK1-mediated regulation of the differentiation and proliferation of neuroblastoma cells." (PMID 34771457, 2021). "We analyzed the effect of the knock-down of LMNA also in the IMR-32 and SMS-KCNR neuroblastoma cell lines." (PMID 23049808, 2012). "In neuroblastoma cell lines, lamin A/C knockdown, rather than upregulation, results in increased migration of neuroblastoma cells." (PMID 33316938, 2020).
arrhythmogenic right ventricular cardiomyopathy (8 papers, 2015 to 2026). "Genetic variants in desmosomal proteins (e.g., PKP2, DSP, DSG2, DSC2) are strongly associated with arrhythmogenic right ventricular cardiomyopathy (ARVC), while mutations in sarcomeric and cytoskeletal genes (e.g., MYH7, LMNA, DES) are linked to hypertrophic and dilated cardiomyopathies." (PMID 41596321, 2026). "The most common subtype of ACM is arrhythmogenic right ventricular cardiomyopathy (ARVC); however, left and biventricular dominant forms of the disease are well documented, including lamin types A/C (LMNA) and phospholamban (PLN) cardiomyopathies." (PMID 32466575, 2020). "Recently, severe forms of arrhythmogenic right ventricular cardiomyopathy (ARVC) have been linked to lamin A/C gene mutations, and both genetic and phenotypic overlap between DCM and ARVC was observed." (PMID 25837155, 2015). "However, over the years, LMNA mutations have been also associated with a combination of morpho-functional phenotypes between DCM and arrhythmogenic right ventricular cardiomyopathy (ARVC), underlining the urge for a new (and wider) classification of cardiac laminopathies." (PMID 30319452, 2018).
Obesity (8 papers, 2016 to 2025). Accumulation of substantial excess body fat. "In adipose tissue, lamin A/C is specifically upregulated in ATMs, in particular in CD11c+ M1 ATMs, by obesity." (PMID 29731750, 2018). "Notably, senescence-associated genes such as ID2, LMNA, CDKN1A, and CTNNB4 were dysregulated in obesity and partially reversed after surgery." (PMID 40847086, 2025). "Since lamin A/C has been linked to type 2 diabetes, we examined whether the expression level of lamin A/C is affected by obesity using a diet-induced obesity model." (PMID 29731750, 2018). "It is also possible that lamin A/C overexpression simply increases retention of Rel A in the nucleus in the context of obesity, which could lead to NF-κB hyperactivation, and thereby further aggravating the inflammatory cascade in already inflamed adipose tissue." (PMID 29731750, 2018). "We found that MORC3, NUP62, CGAS, ABI3, and RPA2 were highly expressed in lean individuals, where as LMNA, ID2, CDKN1A, TENT4B, MME, and MYC were upregulated in the PBMCs of individuals with obesity." (PMID 40847086, 2025). "Transcriptomic analyses further revealed obesity-induced immune cell senescence through regulation of key genes (ID2, LMNA, CDKN1A), which could be reversed by bariatric surgery." (PMID 40847086, 2025). "Transcriptomic analysis further revealed that individuals with obesity had higher expression of cellular senescence-related genes such as ID2, LMNA, and TENT4B in PBMCs compared to lean individuals, with expression levels of these genes significantly decreasing after bariatric surgery." (PMID 40847086, 2025).
osteosarcoma (8 papers, 2012 to 2023). A usually aggressive malignant bone-forming mesenchymal neoplasm, predominantly affecting adolescents and young adults. "Subsequently, nuclear membrane ruptures were identified in human fibroblasts harboring missense or nonsense mutations in LMNA (the gene for lamin A and lamin C) and in cancer cell lines (osteosarcoma cells, HeLa cells)." (PMID 32910721, 2020). "Taken together, knockdown of CNOT1 inhibited osteosarcoma growth through the Hedgehog signaling pathway via its association with LMNA, suggesting a candidate orientation for osteosarcoma treatment." (PMID 28188704, 2017). "prove that CNOT1 cooperates with LMNA to aggravate the occurrence of osteosarcoma by regulating the Hedgehog signaling pathway." (PMID 37377953, 2023). "Significantly, CNOT1 interacts with LMNA (lamin A) in osteosarcoma cells and depletion of CNOT1 suppresses the cell proliferation through the Hedgehog signaling pathway via its association with LMNA." (PMID 33138308, 2020). "Taken together, these results strengthen the conclusion that CNOT1 interacts with LMNA and functions as a positive regulator of LMNA protein in osteosarcoma." (PMID 28188704, 2017). "The results showed that CNOT1 specifically interacted with LMNA in osteosarcoma cells as indicated by the Co‐IP assay." (PMID 28188704, 2017). "More importantly, this report provides, for the first time, experimental evidence and implicates the significance of the interaction between CNOT1 and LMNA in osteosarcoma cells." (PMID 28188704, 2017). "Our data demonstrated that CNOT1 interacted with LMNA and affected its protein stability in osteosarcoma cells." (PMID 28188704, 2017). "In the present study, we found that CNOT1 and LMNA interacted with each other in osteosarcoma cells." (PMID 28188704, 2017). "Lamin A/C knock-down human osteosarcoma cells and embryonic fibroblasts derived from lamin A/C knock-out mice display enhanced proteasomal degradation of pRb." (PMID 23077635, 2012). "These RBPs include NOP58, FAM120C, DYNC1H1, TRAP1, and LMNA, which may serve as molecular targets for osteosarcoma immune regulation." (PMID 37139238, 2023). "Knockdown of CNOT1 affected the protein expression level of LMNA in osteosarcoma cells." (PMID 28188704, 2017). "In addition, CNOT1 was found to interact with lamin A (LMNA) and affect its protein stability in osteosarcoma." (PMID 28188704, 2017). "Finally, we detected the expression of LMNA in osteosarcoma tissues." (PMID 28188704, 2017). "A rescue study showed that the decreased growth of osteosarcoma cells and inhibition of the Hedgehog signaling pathway by CNOT1 depletion were reversed by LMNA overexpression, indicating that the activity of CNOT1 was LMNA dependent." (PMID 28188704, 2017).
osteoporosis (7 papers, 2011 to 2025). A condition of reduced bone mass, with decreased cortical thickness and a decrease in the number and size of the trabeculae of cancellous bone (but normal chemical composition), resulting in increased fracture incidence. "A premature aging disorder, the HGP syndrome is caused by a human lamin-A (LMNA) mutation and presents aged appearances such as osteoporosis and loss of hair." (PMID 37250905, 2023). "In another disease, Mandibular Dysplasia Type A, a mutation in the LMNA leads to osteolysis and osteoporosis." (PMID 34944031, 2021). "Mutations in the lamin A/C gene (LMNA) are identified in patients with various types of laminopathy-containing diseases, which have features of accelerated aging and osteoporosis." (PMID 32479501, 2020). "In atypical progeroid syndrome, age-related pathologies such as osteoporosis and thinning of the cortical structure occurred due to defects in the LMNA gene." (PMID 34944031, 2021). "For example, LMNA mutation leads to Hutchinson–Gilford progeria syndrome (HGPS), characterized by lipodystrophy, aging, joint contracture, and osteoporosis." (PMID 34944031, 2021). "In addition, target interaction network analysis by network-based visual analysis (miRNet) showed that five genes (GAPDH, PLOD1, LMNA, WDR1, and P4HB) with five miRNAs (hsa-let-7a/b-5p, hsa-let-7b-5p, hsa-mir-16-5p, hsa-mir-18a-5p, and hsa-mir-192-5p) were associated with osteoporosis by DisGeNET." (PMID 38132172, 2023). "However, the mechanisms of bone loss and the potential association between lamin A/C deficiency and senile osteoporosis have not been fully explored in a lamin A/C null animal model." (PMID 21547077, 2011). "Additionally, mice lacking lamin A/C showed a decrease in bone formation that exceeds a decrease in bone resorption resulting in significant bone loss mimicking the cellular changes observed in senile osteoporosis." (PMID 21547077, 2011).
autosomal dominant Emery-Dreifuss muscular dystrophy (6 papers, 2007 to 2025). Autosomal dominant form of Emery-Dreifuss muscular dystrophy. "Exome sequencing on this patient detected a pathogenic variant in the LMNA gene (NM_170707: c.C1357T: NP_733821: p.Arg453Trp) that has been reported to cause Autosomal Dominant Emery-Dreifuss muscular dystrophy." (PMID 36253810, 2022). "The genetic dominance of lam effects on Drosophila fitness and pupariation height is similar to the dominance of LMNA mutations in man that cause Autosomal Dominant Emery-Dreifuss muscular dystrophy." (PMID 17565385, 2007).
lung carcinoma (6 papers, 2011 to 2022). "LMNA is a scaffolding protein that contributes to the regulation of the cell cycle in lung cancer tumor cells." (PMID 36139528, 2022). "Low levels of lamin-A/C in lung cancer cells were maintained in the presence of migratory signaling molecules, such as EGF." (PMID 36012358, 2022). "The methylation levels of three CpGs (located at LMNA, SREBF1, and ABCG1) in whole blood were inversely associated with lung cancer risk." (PMID 33939316, 2021). "Previous studies have demonstrated that lamin A/C is overexpressed in A549 cells and is a potential biomarker for early detection of lung cancer." (PMID 29285216, 2017). "Thus, in addition to the previous reports for leukemia and B-cell lymphomas, colon cancer, prostatic cancer, lung cancer, and gastric cancer, lamin A/C is also often lost or reduced in ovarian cancer." (PMID 21439080, 2011). "We treated lung cancer cells with WM-1119, a specific KAT6A/B inhibitor, and examined whether KAT6A/B inhibition induces lamin A/C downregulation." (PMID 36009484, 2022).
melanoma (6 papers, 2021 to 2025). A malignant, usually aggressive tumor composed of atypical, neoplastic melanocytes. "The role of LMNA is well studied in melanoma, however the role of LMNB1 and the corresponding receptor LBR remained unclear so far." (PMID 35883595, 2022). "We first downregulated lamin A and lamin C expression in the nuclei of B16F10 melanoma cells by stably expressing in these cells a lamin A/C shRNA construct targeting exon 8 of the Lmna gene." (PMID 34069191, 2021). "Because the nuclear lamina stiffness is sensitive to the ratio between type A and type B lamins in both mesenchymal and hematopoietic cells, we expected that lamin A/C downregulation would also increase nuclear deformability and squeezing capacities in our melanoma cell model." (PMID 34069191, 2021). "When comparing monocytes to melanoma cells, proteins such as VIM, LMNA, CALU, LGALS3, CTTN, and CORO1A are strongly and confidently differentially expressed." (PMID 40775377, 2025).
myocardial infarction (6 papers, 2016 to 2024). Gross necrosis of the myocardium, as a result of interruption of the blood supply to the area, as in coronary thrombosis. "Hutchinson-Gilford syndrome (HGPS, OMIM 176670, a rare premature aging disorder that leads to death at an average age of 14.7 years due to myocardial infarction or stroke, is caused by mutations in the LMNA gene." (PMID 28033363, 2016).
ovarian carcinoma (6 papers, 2011 to 2024). A malignant neoplasm originating from the surface ovarian epithelium. "The experimental results described here support a hypothesis that nuclear envelope defects (loss of lamin A/C proteins) may be the common cause of chromosomal numerical instability and aneuploidy in ovarian cancer." (PMID 27875985, 2016). "Since lamin A/C is frequently reduced or lost in ovarian cancer cells, we reason that the lamin A/C-deficient ovarian cancer cells may develop aneuploidy by such a mechanism: nuclear protrusions and formation of micronuclei." (PMID 27875985, 2016). "We further speculate that nuclear structural defects as a consequence of the loss of lamin A/C (and also loss of emerin) may be a principal mechanism for the chromosomal numerical instability, and the underlying cause of aneuploidy in ovarian cancer." (PMID 21439080, 2011). "Importantly, LMNA expression is reduced in multiple malignancies, such as gastric or ovarian cancers, while abnormal fusion of LMNA‐NTRK1 gene may cause tumourigenesis." (PMID 38769668, 2024). "It is worth noting that deregulated lamin-A/C (LMNA) expression has been associated with nuclear shape, mechanical stability, and migration ability of cells in ovarian cancer." (PMID 36672361, 2023). "We first tested if known relevant nuclear envelope components in ovarian cancer were deregulated according to cancer nuclear morphological diversification, including LMNA, Lamin B1 and B2, Emerin, nucleoporins NUP88 and NUP1532." (PMID 30254278, 2018). "One report concluded that lamin A/C proteins are increased in ovarian cancer when normal ovarian tissues (instead of ovarian surface epithelia) were used as controls." (PMID 27875985, 2016). "For proteins, emerin is often missing or reduced in ovarian cancer lines and noticeably, lamin A/C proteins are generally reduced in ovarian cancer cells." (PMID 21439080, 2011). "We investigated the expression of the nuclear envelope proteins lamin A/C in ovarian cancer by immunohistochemistry and studied the consequence of lamin A/C suppression using siRNA in primary human ovarian surface epithelial cells in culture." (PMID 21439080, 2011). "Previous studies have established that cellular Lamin A/C is lost or reduced in breast and ovarian cancer cells, and reduced Lamin A/C underlying nuclear envelope distortion and malleability, explaining the mechanism that Lamin A/C is a key determinant of paclitaxel sensitivity." (PMID 38249350, 2023). "Thus, the published studies generally support our report that lamin A/C proteins are lost in over half of ovarian cancer." (PMID 27875985, 2016). "Thus, we conclude that the lamin A/C-suppressed cells achieved aneuploidy and a chromosomal distribution similar to the aneuploid ovarian cancer cells (OVCAR5 and OVCAR3)." (PMID 21439080, 2011).
Skeletal myopathy (6 papers, 2010 to 2025). "Dominant LMNA gene mutations cause multiple human diseases including cardiac and skeletal myopathies." (PMID 21179469, 2010). "In addition to DCM in the first decades of life, Emery–Dreifuss muscle dystrophy (EDMD) generates skeletal myopathy secondary to mutation in the lamin A/C (LMNA) gene with autosomal dominant inheritance or mutation in the EMD gene with X-linked recessive inheritance." (PMID 38337354, 2024).
cardiac conduction disease (5 papers, 2021 to 2024). "Genetic forms of DCM, which are typically characterized by cardiac conduction disorders and are particularly prone to malignant arrhythmias, are linked to mutations in lamin A/C (LMNA), cardiac sodium channel Nav1.5." (PMID 34685747, 2021). "Variants in the LMNA gene, which encodes for Lamin A/C, are associated with cardiac conduction disease (CCD)." (PMID 34806324, 2021). "In no case was a genetic test performed to investigate mutations of SCN5A or LMNA, which may be present in progressive cardiac conduction disease." (PMID 33777448, 2021).
coronary artery disease (5 papers, 2017 to 2023). "As control, we used cardiac muscle tissues from a patient who experienced heart transplantation due to an ischemic heart disease not related to LMNA mutations." (PMID 35846372, 2022).